NRAS (NRAS proto-oncogene, GTPase)
Diseases named in the same sentence as NRAS in open-access papers (continued):
Sharing a sentence is not in itself a finding about the gene and the disease.
cancer (continued). "Increased MAP/ERK kinase (MEK) activity is a feature of many cancers, and is often triggered by missense mutations in BRAF and NRAS, two upstream oncogenes and potent regulators of Ras/Raf/Mek/ERK signaling." (PMID 30838036, 2019). "RAS genes (NRAS, HRAS, and KRAS) are the most common oncogenes in human cancers with high rates of somatic mutations in pancreatic, lung, and colorectal cancers." (PMID 31835496, 2019). "The frequency of these mutations is higher in right-sided tumors, without any significant difference between unselected CRC and KRAS/NRAS/BRAF wt carcinomas." (PMID 31226844, 2019). "Briefly, we found 34 somatic alterations, including eight genes recorded in the cancer gene list, and confirmed recurrent NOTCH1 (SNVs 6/9, indels 1/9), KRAS (SNVs 1/9), NRAS (SNVs 2/9), FBXW7 (SNVs 2/9), and MTOR (SNVs 2/9) mutations (Table EV1)." (PMID 29880602, 2018). "It is known that in cancer cells, NRAS and KRAS are often hyperactivated in comparison with HRAS and therefore NRAS and KRAS are much more important therapeutic targets in cancer when compared to HRAS14,15." (PMID 29891945, 2018). "G-quadruplex–forming sequences are found in telomeres and are enriched in the promoters and untranslated regions (UTRs) of genes, especially cancer-related genes such as NRAS, VEGF and BCL220–27." (PMID 29891945, 2018). "The expression of cancer-related proteins regulated by formation of a G-quadruplex, including NRAS, can be effectively controlled if a ligand can not only bind reversibly but also attack irreversibly DNA and RNA G-quadruplexes." (PMID 29891945, 2018). "A recent CRC study proposed that NRAS mutations were found to be tilted to the right colon and MSI-L cancers." (PMID 29643917, 2018). "Of course, their approach of specifically targeting two cell‐signaling factors downstream of NRAS will require clinical testing to demonstrate benefits for cancer patients." (PMID 29661909, 2018). "We discovered multiple mosaic-activating variants in 4 genes of the RAS/MAPK pathway, KRAS, NRAS, BRAF, and MAP2K1, a pathway commonly activated in cancer and responsible for the germline RAS-opathies." (PMID 29461977, 2018). "In cancer cells, commonly occurring missense mutations in three members of the RAS family genes (HRAS, KRAS and NRAS) result in their constitutive activation." (PMID 29891945, 2018). "The NRAS Q61 mutations found in 12% of SKCM patients are more challenging to treat, as is any RAS-mutant cancer due to activation of multiple signaling pathways." (PMID 30053901, 2018). "•These findings suggest that MEK/ERK signaling through RAC1 and NRAS drives resistance to ER-stress in cancer cells." (PMID 29329780, 2018). "Hyperactivity of the gene NRAS contributes to the proliferation and metastatic nature of many types of cancer cells." (PMID 29891945, 2018). "A known activator of MEK/ERK signalling in cancer is oncogenic NRAS, which directly activates the kinase RAF upstream of MEK." (PMID 29329780, 2018). "The mutations of RAS (KRAS and NRAS), IDH2, EGFR, and PI3K are clinically relevant and well associated in many other cancers." (PMID 28900470, 2017). "RAS genes (HRAS, NRAS and KRAS) are the most frequently mutated oncogene family in human cancers, and is strongly associated with cigarette smoking." (PMID 29137294, 2017). "On the other hand, the damaging CDH1 T340A, damaging NRAS G138R and tolerated MLH-1 R148Q variant were exclusively present in the cancer group." (PMID 29069792, 2017).
cancer (continued). "For example, activating mutations in the KRAS gene prevail in lung, colon and pancreatic cancers, while mutations in NRAS and HRAS are rarely found in these cancer types." (PMID 26799184, 2016). "Mutations in well-known cancer driver genes (BRAF and H/K/NRAS) and fusion gene rearrangements were identified in 37.22%, 25.00%, and 12.78% of total tumors, respectively." (PMID 27494611, 2016). "Malignant tumors frequently exhibited poor expression of miR-32, whose targets include NRAS, PI3K and notably, MCL-1." (PMID 27846237, 2016). "Next, we analyzed 274 mutations in 24 cancer-relevant genes (Sequenom technology), including BRAF, NRAS, KIT c-MET, GNAS and GNAQ." (PMID 27057633, 2016). "We further examined the expression of NRAS, which promotes oncogenesis in various cancers, and found that NEAT1 knockdown significantly reduced NRAS expression in GSCs." (PMID 27556696, 2016). "Known driver genes from the cancer gene census in which we identified missense mutations included MAP3K5 and NRAS (p.Q61K)." (PMID 26414517, 2016). "Five nonsynonymous germline variants on 4 cancer susceptible genes, CDH1, APC, MLH1, and NRAS, were observed in 6 patients with CRC (12%)." (PMID 27121310, 2016). "It has been shown that cancer cells respond to specific drugs when they harbor mutations in driver genes such as BRAF and NRAS." (PMID 27356755, 2016). "Other notable hub genes have also been claimed to be associated with cancers, including MAPK1, MAPK3, JAK2, EGFR, KRAS and NRAS." (PMID 27467251, 2016). "NRAS is also found activated in certain tumor types such as melanoma, whereas HRAS mutations are rarely found in human cancers." (PMID 27330862, 2016). "More recently, new guidelines for the use of cetuximab and panitumumab treatment in CRC patients supported the analysis of the mutational status of both KRAS and NRAS genes and BRAF in wild-type RAS cancers." (PMID 26508446, 2015). "The PentaPanel platform assesses single nucleotide polymorphisms in 56 hotspots of the 5 most clinically relevant cancer genes, KRAS, NRAS, BRAF, EGFR and PIK3CA for a total of 221 detectable mutations." (PMID 26435479, 2015). "In cultured cells, wild-type HRAS, NRAS or KRAS have been shown to promote proliferation of oncogenic RAS-driven cancer cell lines by mediating EGF signaling." (PMID 25902334, 2015). "Members of the MAPK signalling pathway, such as NRAS, KRAS and BRAF are among the most frequently mutated proto-oncogenes in cancer." (PMID 26090869, 2015). "High expression of CIP2A, NRAS, and to lesser extent KRAS was associated with poor prognosis in TCGA pan-cancer data set." (PMID 26278961, 2015). "For NRAS mutant cancers the combination of MEK and the dual PI3K/mTOR were described to be synergistic." (PMID 26544513, 2015). "Our study provides evidence that NRAS mutant cancers share signaling similarities across different malignancies." (PMID 25277205, 2014). "We recently identified somatic activating mutations in genes associated with the AKT and MAPK signaling pathways, including PIK3CA, KRAS, HRAS, and NRAS, in BM from breast and other cancers." (PMID 22567347, 2011). "Examples include members of the MAPK signaling pathway, such as NRAS, a known oncogene; and members of the WNT signaling pathway, DVL2, DVL3, APC and TCF7 which have been previously implicated in colorectal and other cancers." (PMID 19997598, 2009). "To determine the requirement of RAS in these RAS-mutant cancer lines for cellular proliferation, we studied these lines for growth following induction of shRNAs that target NRAS or KRAS." (PMID 19492075, 2009). "Oncogenic mutations in the RAS family of small GTPases, KRAS, HRAS and NRAS, occur in approximately a third of all human cancers." (PMID 19492075, 2009).
cancer (continued). "RAS family proteins, including HRAS, NRAS, and KRAS, are frequently mutated in cancer." (PMID 41986348, 2026). "Single-cell analysis of localized Ras-LOCKR-S demonstrated that a subpopulation of KRas-G12C-driven cancer cells treated with Ras-G12C–GDP inhibitors increased Golgi-localized WT H/NRas activity, which correlates with rebound MAPK signaling and drug-resistant cell growth." (PMID 39103633, 2025). "HRAS-mutated cancers are still potential therapeutic targets of FTIs such as tipifarnib despite the negative results of FTIs against NRAS- or KRAS-mutated cancers." (PMID 40243851, 2025). "KRas-G12C-expressing cancer cells also express wild-type (WT) HRas and NRas (H/NRas), thus WT Ras may have a compensatory role during mutant KRas inhibition." (PMID 39103633, 2025). "Additionally, lncRNA‐SNHG15 has been identified as a regulator of downstream genes such as MYC, NRAS, BAG3, and ERBB3, all of which are closely associated with cancer progression." (PMID 40620190, 2025). "Despite the discovery of NRAS palmitoylation more than two decades ago, the clinical relevance of this modification in treating NRAS‐driven cancers remains unclear." (PMID 40091521, 2025). "The combination of atypical BRAF and other atypical Ras mutations (in KRAS, NRAS, or NF1) is consistent with a “mini-driver” model in which some cancers acquire sufficient Ras activation through a two-step process rather than a single “hit” at BRAFV600E or one of the common KRAS hotspots." (PMID 39751654, 2025). "In human AML cells, ABD957 blocks N-Ras depalmitoylation with higher proteome selectivity than Palm M. ABD957 synergizes with MEK inhibitors to suppress N-Ras signaling and inhibit NRAS-mutant AML growth, suggesting ABHD17 inhibitors as targeted therapies for NRAS-driven cancers." (PMID 40977744, 2025). "Our study hints at the sensitivity of other NRAS-mutant cancer cells to NRAS ASO treatment, which may be addressed independently." (PMID 40473796, 2025). "Interestingly, DHA was found to inhibit the proliferation and facilitate the apoptosis of LLC and A549 with significant anti-cancer efficacy and down-regulation of NRAS." (PMID 38778121, 2024). "Additionally, we found that GOLGA7 is essential for the proliferation and signaling of cancer cells harboring oncogenic NRAS." (PMID 38317235, 2024). "The three main RAS genes mutated in cancer are HRAS, KRAS, and NRAS." (PMID 38982514, 2024). "Comparison with previous studies also shows that the role of KRAS and NRAS genes in other cancers is similar and may be effective in determining molecular pathways of cancer progression." (PMID 39867023, 2024). "BRAF MT tumors were significantly more prevalent in the MSI-H population, constituting 62.8% of this subgroup (p<0.001), while All-WT, KRAS MT, and NRAS MT cancer specimens were less frequent, accounting for 21.1%, 15.4%, and 0.7%, respectively (p<0.001 for each)." (PMID 39628993, 2024). "However, genetic polymorphisms play an important role in increasing the risk of various diseases, including types of cancers, especially some SNPs of KRAS and NRAS genes, which are associated with a higher risk of LSCC." (PMID 39867023, 2024). "Targeting NRAS mutant cancers is challenging and treatment strategies include targeting NRAS-regulated mitogen activated protein kinase (MAPK)/extracellular signal-regulated kinase (ERK) signaling pathways either alone or in combination with PI3K inhibitors or immunotherapies." (PMID 38982514, 2024). "Finally, increased production of proinflammatory cytokines and chemokines by cancer cells was shown to be induced by NRAS oncoprotein, which elevated expression was also observed in resistant cell lines." (PMID 39175042, 2024).
cancer (continued). "The three main RAS genes that are frequently mutated in human cancers include Harvey rat sarcoma viral oncogene homolog (HRAS), Kirsten rat sarcoma viral oncogene homolog (KRAS), and Neuroblastoma ras viral oncogene homolog (NRAS)." (PMID 38982514, 2024). "The observation in cancer databases of preferential amplification of KRAS versus HRAS or NRAS might seem counterintuitive if it is already the most abundant isoform." (PMID 36864243, 2023). "This central position to orchestrate hallmarks of life may explain why RAS is so frequently exploited in cancer, where the three RAS genes, KRAS, NRAS and HRAS combined are mutated in 19% of cancer patients." (PMID 36688434, 2023). "Droplet digital PCR (ddPCR) analysis of the fraction of KRAS/NRAS/BRAF mutated gene copies in kinase-rearranged tumors indicated that there was simultaneous co-occurrence of two activating events in cancer cells, but not genetic mosaicism." (PMID 37686416, 2023). "The findings suggest that targeting RAB27B by blocking the palmitoylation of NRAS could provide a promising therapeutic strategy for NRAS-driven cancers." (PMID 37317974, 2023). "For example, Selumetinib and Binimetinib targeting NRAS may be useful to patients in the normal-PI branch in the early cancer stage." (PMID 37228122, 2023). "The findings suggest that targeting RAB27B could provide a promising therapeutic strategy for NRAS-driven cancers." (PMID 37317974, 2023). "Mutations of other isotypes, NRAS and HRAS are found in many human cancers as well." (PMID 37221195, 2023). "To address this gap, we assessed the prognostic and predictive value of vitamin C in patients with stage IV CRC by comparing vitamin C level between cancer-free and cancer patients and analyzing the specific plasma vitamin C levels in RAS (NRAS/KRAS) and BRAF mutated CRC patients." (PMID 36969825, 2023). "The three human Ras genes, HRAS, KRAS, and NRAS, are found frequently mutated in about one-third of human cancers, with KRAS mutations being the most prevalent among the three isoforms (∼86% of cases), and with NRAS and HRAS representing only 11% and 3%, respectively." (PMID 38051103, 2023). "NRAS at 11%, while HRAS accounts for only ~3% of all RAS mutation-dependent cancers." (PMID 37892237, 2023). "MicroRNA-708 restoration also weakened cancer cell motility in an NRAS-independent manner." (PMID 37083947, 2023). "Similar to NRAS, many oncogenes in cancer are still deemed intractable." (PMID 37083947, 2023). "The eighth edition of the AJCC Cancer Staging System is focused on the individual treatment and prognostic factors of CRC based on molecular biomarkers, such as BRAF, KRAS, and NRAS that are associated with chromosomal instability, mismatch repair, and microsatellite instability." (PMID 36142151, 2022). "NRAS is a RAS family member, that works as a switch regulating GDP/GTP, which encodes GTPase (membrane-bound protein) activity and is a key regulatory factor in multiple biological processes that affect cancer survival and progression." (PMID 36348379, 2022). "Our findings provide key insights that may help predict drug treatment response and enhance our understanding of pan-cancer multi-drug resistance in the context of mutant NRAS signaling and any other selected signaling pathways." (PMID 35534592, 2022).
cancer (continued). "Furthermore, SET/CIP2A overexpression was frequently observed in cancers with mutations in various oncogenes (e.g., EGFR, KRAS, NRAS, and BRAF)." (PMID 36463234, 2022). "Numerous cancer cell lines exhibit a strong correlation or dependency on mutant H/K/NRAS and SHOC2." (PMID 35768504, 2022). "Considering the sequence homology between RAS isoforms is 100% identical within the Switch II region, we asked whether the interaction between AGO2 and HRAS or NRAS could be detected endogenously in human cancer cell lines." (PMID 35923912, 2022). "For example, targeting PI3K–Akt signal pathway to produce antileukemia effect is to use it to activate upstream oncogenes (such as Flt3–ITD, KIT, and NRAS), and calcium homeostasis disorder plays an important role in the pathogenesis of different kinds of malignant tumors." (PMID 36452344, 2022). "NRAS are the prevalent oncogenes contributing 16–25% among all cancers." (PMID 36430761, 2022). "NRas is a key mediator of the mitogenic pathway in normal cells and in cancer cells." (PMID 36304112, 2022). "The RAS proteins HRAS, KRAS, and NRAS (H, K, NRAS) are RAS oncoproteins that cause human cancers." (PMID 35409064, 2022). "However, more recent investigations have shown that HRAS, NRAS and KRAS, when mutated, are each associated with a distinct group of cancer types." (PMID 35204676, 2022). "This shows that fitness defects caused by SHOC2 inactivation in cancer cell lines are directly associated with the oncogenic activity of H/K/NRAS and are independent of MRAS." (PMID 35768504, 2022). "To further validate that RAS84 expression could predict high RAS activity in RAS mutants in individual cancers, we looked at pan-RAS mutation (KRAS, NRAS, HRAS) distributions across RI values per cohort." (PMID 36163168, 2022). "Thus, ACA-28 and/or GT-7 were shown to induce apoptosis in cancer cell lines with different oncogenic mutations, ranging from HER2, BRAF, NRAS, and KRAS." (PMID 35203351, 2022). "CTNNB1, KRAS, and NRAS are also three intersecting genes in the cancer pathway in this study, indicating that they may be key target genes regulating the development of AIS." (PMID 36399471, 2022). "NRAS is a GDP binding gene, an important component of the RAS pathway associated with many cancers." (PMID 33718231, 2021). "FTIs were found to lack anti-tumor effect in KRAS (and NRAS) mutant cancers." (PMID 34947990, 2021). "In fact, the founding members of the RAS gene family in humans (KRAS, NRAS and HRAS) are the most common oncogenes in human cancer, whereas mutations that permanently activate RAS are found in almost 25% of all human tumours and up to 90% in specific types of malignancies." (PMID 34948093, 2021). "Even though mutations in other RAS isoforms, including the neuroblastoma RAS viral (v-ras) oncogene homolog (NRAS) and Harvey rat sarcoma viral oncogene homolog (HRAS) are prevalent in many cancer types, mutations in KRAS account for 85% of all RAS isoform mutations." (PMID 33801965, 2021). "Unfortunately, KRAS and NRAS, the major RAS isoforms that are mutated in adult cancers, can be alternatively prenylated by gerangeranyltransferases, and FTIs failed in Phase III clinical trials for KRAS-mutated colorectal and pancreatic cancers." (PMID 33924994, 2021). "In our previous study, we demonstrated that dual inhibition of ACK1 and GCK by multi-targeted kinase, GNF-7 and its derivatives, displays strong capabilities of cellular inhibition on both Ba/F3 cells transformed with NRAS-G12D and OCI-AML3, a human cancer cell harboring NRAS-Q61L mutation." (PMID 34956887, 2021).